IL2 (interleukin 2)
Diseases named in the same sentence as IL2 in open-access papers (continued):
Sharing a sentence is not in itself a finding about the gene and the disease.
tumor (continued). "First, we found a significantly increased secretion of IL-2 from total lung cells derived from tumor bearing STAT1 KO mice compared to tumor bearing Bl6/C57j mice." (PMID 30647851, 2018). "Preclinical animal models and more recently phase I/II clinical trials have shown that IL-2 immunocytokines can avoid the severe toxicities of the systemic administration of high doses of soluble IL-2 maintaining the potent anti-tumor effect of this cytokine." (PMID 30619269, 2018). "Restored the NK activity and the IL-2 and IFNy production of the spleen cells, which were suppressed by the tumor." (PMID 30410443, 2018). "It has been shown by Parkhurst and colleagues that anti-CEA CAR-T cells proliferate in response to tumors overexpressing CEA, resulting in IL-2 and IFNγ cytokine secretion and tumor cell lysis." (PMID 30103457, 2018). "In this model, production of IFN-γ, IL-2, and TNF-α showed a sharp threshold dependence on tumor antigen density and there was a significantly higher threshold for IL-2 production compared to IFN-γ production." (PMID 30416506, 2018). "Briefly, dCAR-T cells in mice bearing the cognate tumor cells (AsPC-1) released high levels of cytokines, including 2320 pg/mL IL-2, 609 pg/mL TNFα, 2486 ng/mL IL-6, and 67 ng/mL IFNγ, which was similar to that observed for cytotoxicity." (PMID 30103775, 2018). "One day after three injections of αCD137/IL-2-Fc therapy in tumor-bearing mice, tumors and blood were collected and subjected to flow cytometry analysis for lymphocytes counts, cytokine production, and biomarker analysis." (PMID 29295974, 2018). "It is known that the CD8+ T lymphocytes, which have the NK-activating receptor NKG2D on their surface, acquire an NK-like activity and the ability to kill the HLA-negative tumor cells after a prolonged incubation with the IL-15 or IL-2 cytokines." (PMID 29850628, 2018). "Cytokines play an important role in the immune response, we investigated the effect of the combination of SEP and αPD-L1 on the production of cytokines IFN-γ and IL-2 in spleen and tumor of B16-F10-bearing mice using ELISA kits." (PMID 29317734, 2018). "Overall, despite the observation that IL-2/CD40 alleviates certain suppressive functions in elderly tumor-infiltrating CD8+ T cells, these cells also demonstrated reduced anti-tumor effector function." (PMID 30560130, 2018). "In order to assess the impact of macrophage depletion on T cell function, in vivo anti-tumor CTL analyses was performed in IL-2/anti-CD40 treated mice ± macrophage depletion." (PMID 30459812, 2018). "Tumor growth was effectively suppressed after the treatment with either αCD137/IL-2-Fc or Lipo-αCD137/Lipo-IL-2-Fc." (PMID 29295974, 2018). "In this study, we have explored a variety of IL-2 constructs expressed by a tumour-selective oncolytic vaccinia virus, designed to maintain IL-2 in the tumour microenvironment to reduce systemic toxicity." (PMID 30410056, 2018). "We have shown that the pro-inflammatory cytokines IFN-γ, TNF-α, and IL-2 enhance the capacity of TCR-transfected T cells to lyse tumor target cells;28 by contrast, the addition of autologous monocytes mimics the PD-L1hi environment of the liver." (PMID 30217730, 2018). "Here, we show that Lnc-Tim3 is upregulated and negatively correlates with IFN-γ and IL-2 production in tumor-infiltrating CD8 T cells of HCC patients." (PMID 29706626, 2018). "Lipo-αCD137/IL-2-Fc significantly suppressed tumor progression in the lung and enhanced survival comparing to untreated and Lipo-IgG groups, with 20% of animals achieving complete tumor eradication." (PMID 29295974, 2018). "At different E/T ratios starting from 5:1 to 40:1, HDMAPP-activated γδ T cells in the presence of IL-2 efficiently lysed zoledronate-treated tumor cells lines (AW13516, COLO-205, and Raji)." (PMID 30072989, 2018).
tumor (continued). "We have shown that an oncolytic adenovirus expressing IL-2 and TNF-α enhanced the efficacy of mesothelin-redirected CAR T cells, which was associated with enhanced T cell infiltration to the tumor bed and reduced metastases." (PMID 30416506, 2018). "Administration of IL-2 to activate NK cells in cancer patients led to varied results, depending on the type of tumor tested and the experimental conditions." (PMID 30072983, 2018). "IFNγ and IL-2 cytokine production was observed only when TAG72-BBζ CAR T cells were co-cultured with antigen-positive tumor targets, OVCAR3, LS174T, and OV90." (PMID 30510550, 2018). "This is demonstrated in our animal models, where increased tumour burden leads to increase viral replication and toxic amounts of circulating IL-2 when expressed as a secreted protein." (PMID 30410056, 2018). "Tumor- reactivity of transduced T cells was determined after expansion in media supplemented with IL-2, IL-7, and IL-15." (PMID 30400835, 2018). "The secretion of IFNγ and TNFα by NK cells in response to tumor target stimulation (DAOY) following overnight treatment with IL-2 was measured in supernatants at Day 7, 14, and 1 week, 3 weeks, and 1 month (33 days) post-expansion." (PMID 30400618, 2018). "EGCG also reduced PD-L1 mRNA expression in F10-OVA cells and partially restored interleukin-2 (IL-2) mRNA expression in tumor-specific T cells in a co-culture experiment." (PMID 30126206, 2018). "We next evaluated the relative anti-tumor efficacy and safety of immunoliposomes compared to the free IL-2-Fc/αCD137 combination therapy." (PMID 29295974, 2018). "Following 5-day IL-2 re-culture, CD16 pre-activated NK cells exerted enhanced antibody-independent cytotoxicity and IFN-γ production upon restimulation with cytokines or tumor cells compared to IL-2 cultured NK cells." (PMID 30546366, 2018). "In an experimental lung metastasis model, sensitive to IL-2 therapy, this IL-2 mutant showed similar levels of tumor inhibition to IL-2 but elicited lower levels of morbidity as scored by general health examination." (PMID 30319612, 2018). "Adoptively transferred CD8+ T cells specific for melanoma antigens accumulate in tumor-draining lymph nodes at early time points after vaccination with peptide-pulsed DCs and IL-2 immunotherapy, and subsequently in the BM and primary tumor site." (PMID 30477280, 2018). "Here we show that combination therapy with anti-CD137 and an IL-2-Fc fusion achieves significant initial anti-tumor activity, but also lethal immunotoxicity deriving from stimulation of circulating leukocytes." (PMID 29295974, 2018). "In order to confirm that IL-2 had a protective effect against tumor development in our model, mice were i.n. administered with a recombinant strain of L. lactis which secretes murine IL-2 (LL-IL2)." (PMID 30687269, 2018). "Then, we blocked IL-2 synthesis using neutralizing monoclonal antibodies in mice that were challenged with lethal levels of tumor cells; this led to a significant reduction in the protective abilities of BL23." (PMID 30687269, 2018). "Quantification of total anti-CD137/IL-2-Fc signal in tumor sections showed at 4.5-fold increase in uptake of the combined therapeutics in the liposomal form compared to the free drugs (p < 0.001)." (PMID 29295974, 2018). "Inhibition of macrophages in elderly mice improved the response to IL-2/anti-CD40 immunotherapy leading to a reduction in tumor growth and improved survival (78%)." (PMID 30459812, 2018). "Combining the IT injection of microparticles encapsulating IL-2 with microwave coagulation—to induce tumor cell death—resulted in a systemic tumor-specific immune response in mice bearing lung or hepatocellular carcinomas." (PMID 30619273, 2018). "Previously, we have shown that CD3+CD4+CD25+ lymphocytes activated by IL-2 killed HLA-negative tumor cells through the FasL-Fas interaction." (PMID 29850628, 2018).
tumor (continued). "After two doses, IL-2/CD40 slowed tumor growth rates in both age groups, although the effects in terms of tumor size and weights were more pronounced in young mice, relative to PBS diluent controls." (PMID 30560130, 2018). "We identified an association of TAA-reactive T-cells (defined by IFN-γ production) in correlation with the histopathological grading of the tumor and T-cells cultured with IL-2/IL-15 and IL-21." (PMID 29058035, 2018). "Actually, we also found tissue oedema and increased IL-2 in sera from vvDD-IL-2-treated mice in the early-stage tumour model." (PMID 30410056, 2018). "Altogether, these data suggest that the IL-2 signaling pathway plays an important role in the ability of BL23 to control tumor development in the HPV-induced model of cancer." (PMID 30687269, 2018). "As a result, expression of CD39, A2AR, A2BR, ICOS and LAG-3 was higher on tumor-associated CD8+ T cells from young, compared to elderly, IL-2/CD40-treated mice." (PMID 30560130, 2018). "At the same time, these constructs showed monovalency and high-affinity tumor targeting as compared to classical IL-2 based immunocytokines." (PMID 30619269, 2018). "Using high and low avidity transgenic tumor reactive CD8+ T-cells specific for tyrosinase-related protein-2 (TRP2) we investigated how IL-2 alone or IL-12/IL-2 priming affected these two different T-cell populations." (PMID 30400835, 2018). "We next tested cytokine secretion and verified that Axl CAR-expressing human primary CD8+ T cells secreted high level of IFN-γ and IL-2 only when they were co-cultured with Axl+ K562 tumor cells." (PMID 29497107, 2018). "It is well-established that IL-2 can trigger T lymphocytes to expand and acquire a therapeutic anti-tumor activity." (PMID 30619269, 2018). "IL-12 is even more efficient than IL-2 in activation of NK cells, and also has a potent anti-tumor activity through augmentation of the cytotoxic activity of NK cells, activation of CD8+ T cells, and the inhibition of angiogenesis." (PMID 29316666, 2018). "IL-2 is also important in the regulation of the immune response, including antibody responses, hematopoiesis, and tumor surveillance." (PMID 30619280, 2018). "Use of IL-2-Fc fusions to increase the half-life of IL-2 increase anti-tumor efficacy but still induce substantial toxicity at functional doses." (PMID 29295974, 2018). "The use of IL-2 as an antineoplastic agent has been limited by the serious toxicities accompanied by the doses required to fight the tumor." (PMID 30057605, 2018). "Coculture experiments demonstrate a synergism of gene-modified CD4+ and CD8+ T cells for anti-tumor activity, which was dependent on IL-2 secretion from CD4+ T cells." (PMID 30214445, 2018). "Its delivery of IL-2 to the tumor location in vivo was significant, and it enhanced antigen-specific T cell immune response and controlled tumor growth." (PMID 29316666, 2018). "Poorer CTL responses in elderly mice is likely to contribute to their reduced tumor responses to IL-2/CD40-treatment." (PMID 30560130, 2018). "NKTR-214 is a robust agonist of the IL-2 pathway and together with nivolumab promotes immune activation in the periphery and tumor microenvironment for significant clinical activity." (PMID 30400822, 2018). "They found that response to HD IL-2 correlated positively with tumor expression of PD-L1 (p = 0.01), and that durable remissions also correlated with PD-L1 expression (p < 0.01)." (PMID 29261796, 2017). "Pmel-1 T cells expanded in IL-15 exhibit enhanced tumor immunity compared with those expanded in IL-2." (PMID 28239463, 2017). "Even at a decreased dose of lymphocytes (10 million cells/mouse) the IL-2, IL-21, IL-2/21, IL-7/15 and IL-7/15/21 groups were significantly better at slowing or decreasing tumor growth than the control or the cyclophosphamide-alone groups (all p < 0.0001)." (PMID 28146052, 2017).
tumor (continued). "There are a few studies reporting on either immune checkpoint blockade, intrathecal interleukin 2 (IL-2), or intrathecal tumor-infiltrating lymphocyte (TIL) therapies." (PMID 29069871, 2017). "Our BsAb can inhibit HGF-induced growth and migration of c-MET-addicted tumor cells, promote the apoptosis of tumor cells, and rescue IL-2 secretion of Jurkat T cells." (PMID 28404966, 2017). "IL-2 is a cytokine widely known to promote proliferation with a broad range of implications in tumor growth and control." (PMID 28052005, 2017). "Another approach to enhancing the immunotherapeutic effect of IL-2 involves the combination of localized radiation (producing tumor antigen release) followed by high dose IL-2." (PMID 29254506, 2017). "This platform was combined with systemic administration of tumor antigen-specific antibodies, IL-2, and anti- PD-1 antibodies." (PMID 28220118, 2017). "Because IL-2 drives CD8+ T cells toward an “effector” phenotype, which confers poor anti-tumor performance in some models, reducing IL-2 signaling favors the production of memory CD8+ T cells." (PMID 29123649, 2017). "In preclinical studies, the fusion of L19 with IL-2 has shown potent tumor-targeting effects and therapeutic efficacy in orthotopic models of hepatocellular carcinoma and pancreatic cancer." (PMID 28067804, 2017). "For TIL therapy, in which T lymphocytes are enriched from tumor biopsies, patients are typically lymphodepleted and receive high-dose interleukin-2 (IL-2)." (PMID 28421069, 2017). "For mice in the tumor model group and 5-FU group, the levels of glutamine, TNF-α, IL-2, and BCAAs were all lower than those of the control group, indicating that both the tumor mice and chemotherapy mice were immunocompromised." (PMID 29190948, 2017). "We observed that treatment with a reversible proteasome inhibitor bortezomib (1 mg/kg body weight) in tumor-bearing mice significantly enhanced the expression of lymphocyte-stimulatory cytokines IL-2, IL-12, and IL-15." (PMID 28052005, 2017). "In different tumor mouse models, T cells expanded from OKT3-28BB/CD86/4-1BBL RNA electroporation showed anti-tumor activities superior to those of OKT3/IL-2 T cells and similar to those of CD3/CD28 Dynabead T cells." (PMID 28523432, 2017). "Neither Zsgreen or mock-transduced T cells released IFN-γ or IL-2 when cultured with any of the three tumor cell lines." (PMID 29261129, 2017). "High‐dose IL‐2 is approved in cancer therapy, where it promotes tumour killing by activating NK cells and CD4+ and CD8+ effector T cells 12; however, pulmonary vascular leakage occurs as a side effect to this treatment." (PMID 28176332, 2017). "TIL expansion is accomplished by culturing of small tumour fragments in the presence of IL2, and young TILs are defined as pooled cultures of > 5 × 107 total cells originating from approximately 24 fragments." (PMID 28423678, 2017). "When EnAd-infected tumor cells were incubated with DCs and T cells, the T cells showed a high level of activation as measured by production of IL-2, gamma-interferon, and CD69." (PMID 28345021, 2017). "In contrast, anti-inflammatory cytokines (IL-2, IL-15, and IL-21) usually activate the antitumor immunity and interfere with tumor development." (PMID 28927416, 2017). "DC-CIK cells not only eradicated residual tumor cells but also enhanced immune surveillance capacity of host cells by producing pro-inflammatory cytokines, such as IL-2 and IFN-γ to prevent or delay tumor recurrence." (PMID 29179719, 2017). "Other novel immunotherapy agents such as ALT-801, a tumor-targeted IL-2, and ALT-803, an IL-15 superagonist complex, have also shown activity in UC." (PMID 28134806, 2017). "In the late 1970s, the ability to grow CTL cultures using IL-2 allowed for screening of tumor-derived DNA libraries to characterize tumor antigens." (PMID 29276510, 2017).
tumor (continued). "Strikingly, treatment with IL-2WTFc resulted in a substantial reduction of tumour growth compared to either IL-2/mAb immune complex or the IL-23XFc triple mutant." (PMID 28497796, 2017). "A significant increase of IFN-y and IL-2 mRNA was indeed reported following experimentally-induced tumor regression." (PMID 28829805, 2017). "Infiltration of immune cells was studied in benign and malignant cell spheroids, where it was found that stimulation of human peripheral blood mononuclear cells (PBMCs) by tumor cells or IL-2 was necessary for the infiltration of PBMCs into the spheroids." (PMID 27858101, 2017). "Th1 cytokines, including IFN-γ, IL-2, and TNF-α, enhance the cytotoxicity of CIK cells, whereas Th2 cytokines like IL-6 and IL-10 is associated with tumor immune escape." (PMID 28404886, 2017). "Only after activated PD-1+ CD8+ T cells migrated to the tumor and bound to PD-L1 were cytokines (IL-2 and IFN-γ) produced, stimulating the cytolytic activity of CD8+ T cells and finally causing the exhaustion or dysfunction of T cells." (PMID 29156738, 2017). "These lymphocytes are as effective as IL-2-expanded cells at slowing tumor growth or curing tumors, even at low doses of cells or with large starting tumors." (PMID 28146052, 2017). "Studies in mouse tumor models have similarly shown that senescent T cells exhibit in vivo defects including reduced survival, proliferation, IL-2 production, lymphoid homing, and tumor rejection." (PMID 29387064, 2017). "Not only the number of tumor-reactive T cells was increased but also the percentage of polyfunctional T cells producing the inflammatory cytokines IFNγ and IL-2 was increased." (PMID 28401257, 2017). "Th1 Lymphocytes produce Interferon Gamma (IFN-γ), Tumor Necrosis Factor Alpha (TNF-α), and Interleukin-2 (IL-2), which are all essential for tumor rejection." (PMID 28473858, 2017). "On the other hand, combined therapy with histone deacetylase inhibitors and high-dose IL-2 reduced tumor growth from 1900 mg to 200 mg considering however the toxicity of IL-2." (PMID 28620146, 2017). "Combination of anti-CD40 with IL-2 has been shown to induce delayed growth and regression across several murine tumor models." (PMID 28428882, 2017). "We have observed similar discrepancies between IL-2 ELISA and the MACSPlex assay when released cytokines were analyzed including for example for T cells redirected to different tumor cells via different bispecific abs (Bachmann, unpublished)." (PMID 28404896, 2017). "Several approaches aimed to limit the side effects of IL-2 systemic therapy by targeting IL-2 to the tumor milieu and restricting its effects on the other organs." (PMID 28927416, 2017). "For this purpose, we utilized a dosing regime consisting of five consecutive daily intraperitoneal (i.p.)injections of 1 μg antibody-complexed IL-2 or IL-2-Fc molar equivalent starting 1 day after subcutaneous injection of tumour cells." (PMID 28497796, 2017). "Tumor-reactive murine CD8 αβ T cells expanded ex vivo using IL-15 or IL-7/IL-15 mediate increased tumor immunity in vivo as compared to cells grown in IL-2." (PMID 28239463, 2017). "The activated APCs induce T cells proliferation by the secretion of IL-2 and IL-12 at the tumor site." (PMID 29213157, 2017). "NKTR-214 was invented to harness the potent immune stimulatory benefits of the IL2 pathway to maximize anti-tumor responses and minimize unwanted biological side effects." (PMID 28678791, 2017). "Cytotoxic T lymphocytes (CTL) play an important role in tumor immunity, stimulated by Th1 cells, IL-2, and IFN-γ." (PMID 28406993, 2017). "The cytokines IL-2 and IL-12 although considered to be pro-inflammatory, they negatively regulate tumor behavior, and are currently in clinical use/trials." (PMID 28830415, 2017). "Immunostimulatory cytokines (e.g., IL-2, IL-12, IL-15) support lymphocyte differentiation and survival enabling tumor control." (PMID 28052005, 2017).